VEGFC (vascular endothelial growth factor C)
Description:
Growth factor active in angiogenesis, and endothelial cell growth, stimulating their proliferation and migration and also has effects on the permeability of blood vessels. May function in angiogenesis of the venous and lymphatic vascular systems during embryogenesis, and also in the maintenance of differentiated lymphatic endothelium in adults. Binds and activates KDR/VEGFR2 and FLT4/VEGFR3 receptors.
Synonyms: VEGF-C; Flt4-L; VRP; LMPH1D; LMPHM4
Tractability: Antibody: UniProt places it where antibodies can reach, with high confidence; its Gene Ontology location is reachable by antibodies, with high confidence; UniProt predicts a signal peptide or a membrane-spanning region. Other modalities: a drug acting on it is in phase 2 or 3 trials.
Target class: Secreted protein
Gene: Protein-coding gene on chromosome 4 (176,683,538 to 176,792,922, reverse strand). Ensembl gene ENSG00000150630.
Subcellular location: Secreted
Pathways (Reactome):
Signal Transduction: VEGF binds to VEGFR leading to receptor dimerization; VEGF ligand-receptor interactions
Hemostasis: Platelet degranulation
Gene Ontology:
Molecular function: chemoattractant activity; protein binding; vascular endothelial growth factor receptor 3 binding; growth factor activity; receptor ligand activity
Biological process: induction of positive chemotaxis; positive regulation of mast cell chemotaxis; vascular endothelial growth factor receptor signaling pathway; vascular endothelial growth factor signaling pathway; positive regulation of cell population proliferation; response to hypoxia; signal transduction; sprouting angiogenesis; substrate-dependent cell migration; angiogenesis; negative regulation of blood pressure; negative regulation of osteoblast differentiation; positive chemotaxis; positive regulation of angiogenesis; positive regulation of blood vessel endothelial cell migration; positive regulation of cell migration; positive regulation of epithelial cell proliferation; positive regulation of mesenchymal stem cell proliferation; positive regulation of protein secretion; regulation of vascular endothelial growth factor receptor signaling pathway; response to xenobiotic stimulus
Cellular component: extracellular region; growth factor complex; platelet alpha granule lumen; membrane
Genetic constraint (gnomAD): Loss-of-function variants: 9 observed, 41.42 expected, observed/expected ratio (o/e) 0.22, 90% interval 0.13 to 0.38. The upper end of that interval is the gene's LOEUF score, 0.38, which puts it in group 1 of 6, group 1 being the genes least tolerant of losing a copy. Missense variants: 477 observed, 522.45 expected, observed/expected ratio (o/e) 0.91, 90% interval 0.85 to 0.99. Synonymous variants: 229 observed, 196.57 expected, observed/expected ratio (o/e) 1.16, 90% interval 1.04 to 1.3.
Homologues: Orthologues: chimpanzee VEGFC (99% identical), macaque VEGFC (96% identical), dog VEGFC (90% identical), pig VEGFC (90% identical), rabbit VEGFC (90% identical), guinea pig VEGFC (87% identical), mouse Vegfc (85% identical), rat Vegfc (85% identical), tropical clawed frog vegfc (69% identical), zebrafish vegfc (55% identical). Paralogues in human: VEGFD (33% identical), VEGFA (14% identical), PGF (12% identical), VEGFB (9% identical).
Diseases named in the same sentence as VEGFC in open-access papers:
VEGFC is named in the same sentence as 372 diseases in open-access papers, as found by Europe PMC text mining. Sharing a sentence is not in itself a finding about the gene and the disease. The quoted sentences say what the papers report.
breast carcinoma (178 papers, 2004 to 2026). "STAT3 is also implicated in VEGFC/VEGFR3 signaling during breast cancer." (PMID 38218743, 2024). "In a study by Timoshenko, chitin hydrolysate, a highly concentrated form of chitin, appeared to promote the expression of the vascularization factor vascular endothelial growth factor C (VEGF-C) on the MDA-MB-231 (human breast cancer) cell line." (PMID 39530850, 2025). "Increased VEGFC/VEGFR-3 signaling has been linked to lymphatic metastasis in various cancers, including recent reports in pancreatic and breast cancer." (PMID 41333209, 2025). "As evidence that VEGFC contributes to breast cancer progression, overexpression of VEGFC in an orthotopic mouse model of breast cancer showed increased intratumoral lymphangiogenesis alongside increased metastasis to lymph node and lung." (PMID 38218743, 2024). "Human breast cancers with a high expression of VEGFC are characterized by higher LVD in tissues biopsied from tumors, increased lymph node metastasis, distant metastasis and a worse prognosis." (PMID 38218743, 2024). "Pain following breast cancer treatment is significantly associated with the inflammatory cytokine gene IL13 and lymphatic gene VEGFC." (PMID 35037883, 2022). "Because ZKSCAN5 improved the secretion of VEGFC by breast cancer cells, the effects of the conditioned medium on HLEC proliferation and migration were investigated in ZKSCAN5 knockdown stable cell lines." (PMID 35600335, 2022). "To the best of our knowledge, here, for the first time, we uncovered the function of ZKSCAN5 in modulating VEGFC expression, lymphangiogenesis, and breast cancer cell growth." (PMID 35600335, 2022). "Recent studies showed HIF-1 signaling was involved in lymphatic invasion through induction of platelet-derived growth factor B (PDGF-B) in breast cancer, vascular endothelial growth factor C (VEGF-C) and SP1 in ESCC." (PMID 35752862, 2022). "This is in line with data from a murine breast cancer model demonstrating that upstream inhibition of COX2 in macrophage leads to downregulation of VEGFA, VEGFC and MMP9 associated with reduced metastasis." (PMID 36551640, 2022). "Increased lymphangiogenesis in tumors due to induction of vascular endothelial growth factor C (VEGF-C) promotes metastatic spread in melanoma, breast carcinoma, and colorectal cancer." (PMID 35372032, 2022). "The expression of VEGFC was significantly higher than that of VEGFD in patients with breast cancer, as revealed by investigating TCGA database (p < 0.0001)." (PMID 35600335, 2022). "Clinically, the expression of ZKSCAN5 was frequently upregulated in patients with breast cancer and positively correlated with the expression of VEGFC and the number of lymphatic microvessels." (PMID 35600335, 2022). "Breast cancer-derived vascular endothelial growth factor-C (VEGF-C) has been shown to enhance lymphangiogenesis in lymph nodes to accelerate cancer metastasis." (PMID 31390756, 2019). "A recent meta-analysis indicated that higher tumoral expression of vascular endothelial growth factor C (VEGF-C) was related to poorer relapse-free and overall survival in breast cancer patients." (PMID 29963266, 2018). "The prognostic significance of vascular endothelial growth factor C (VEGF-C) expression in breast cancer (BC) patients remains controversial." (PMID 27812168, 2016). "Survivin promoted breast cancer lymphatic metastasis through cooperation with vascular endothelial growth factor-C (VEGF-C)." (PMID 27340370, 2016). "Similar to our results, high expression of PKM2 and vascular endothelial growth factor-C, an important molecule in angiogenesis and lymphangiogenesis, correlated significantly with poor prognosis in breast cancer." (PMID 27384996, 2016). "SNS regulation of VEGFC expression was also confirmed in 66cl4 mammary tumours from immunocompetent mice or in mammary tumours from MMTV-PyMT transgenic mice." (PMID 26925549, 2016).
breast carcinoma (continued). "Previously, we identified that key molecules (IL6, CSF2, CCL5, VEGFA, and VEGFC) secreted by tumor cells and stromal cells in basal breast cancer can promote metastasis." (PMID 26173622, 2015). "It remains to be determined if VEGFA and its receptor VEGFR2 and VEGFC and its receptor VEGFR3, and CSF2 and its receptor GMRA/GMRB can also serve as therapeutic targets for HER2+ breast cancer since the associations we found were modest." (PMID 26173622, 2015). "The increased expression of VEGFC in TNBC samples found here has also been demonstrated in IHC of breast cancer sections, where VEGFC stained positively in TNBCs significantly more often than in non-TNBCs." (PMID 23667446, 2013). "This study aims to detect the difference in expression between survivin and vascular endothelial growth factor-C (VEGF-C) in treated breast cancer cells and tissues, and to analyze the correlation among survivin, VEGF-C and lymphatic metastasis." (PMID 22607367, 2012). "Neuropilin-2 (Nrp2) is a receptor for vascular endothelial growth factor-C (VEGF-C), which is a well-known lymphangiogenic factor and plays an important role in lymph node metastasis of various human cancers, including breast cancer." (PMID 19580679, 2009). "Correlation between levels of cyclooxygenase-2 (COX-2) and vascular endothelial growth factor-C (VEGF-C) expression in human breast cancer." (PMID 18190720, 2008). "This study aimed to evaluate the correlations of angiogenic biomarkers, specifically the angiopoietin (ANG)‐Tie system and vascular endothelial growth factor‐C (VEGF‐C), with lymphangiogenesis and the related histopathological characteristics in Iranian women with breast cancer." (PMID 40348609, 2025). "In addition, increased protein expression of VEGFC has also been observed in tumors such as ovarian carcinoma and breast cancer." (PMID 38203550, 2023). "ZKSCAN5 was positively related to VEGFC expression in breast cancer tissues (p = 9.0 × 10−6)." (PMID 35600335, 2022). "SIX1 could induce vascular endothelial growth factor-C expression, leading to cell migration in breast cancer." (PMID 35287543, 2022). "To determine the possible transcription factors regulating VEGFC transcription, we selected a transcription factor from the full-length cDNA transfection array of zr75-1 breast cancer cells from −1,058 to +1 bp by using the VEGFC promoter-luciferase (VEGFC-Luc) reporter." (PMID 35600335, 2022). "ZKSCAN5 binds to the promoter section (−2,911 to −2,859 bp) of VEGFC in breast cancer cells." (PMID 35600335, 2022). "By regulating breast cancer-secreted VEGFC, ZKSCAN5 could induce the tube formation of lymph endothelial cells, which promotes tumour proliferation, migration, and metastasis." (PMID 35600335, 2022). "However, VEGFC levels are very low in three out of five breast cancer cell lines and NRP2 levels are very low in all the breast cell lines including MDAMB231." (PMID 33461580, 2021). "LyP-1 accumulated in the tumor lymphatics but not the tumor blood vessels of several tumor xenograft models including osteosarcomas, prostate and breast cancers, and metastatic lymph nodes of the vascular endothelial growth factor C (VEGF-C) overexpressing MDA-MB-435 tumors." (PMID 33918106, 2021). "VEGFC was significantly upregulated in LECs co-cultured with breast cancer compared to control." (PMID 33277521, 2020). "Similarly, soluble VEGFR-3 protein has been shown to inhibit VEGFC-induced tumor lymphangiogenesis and metastatic spread in a breast cancer mouse model." (PMID 32132179, 2020). "Others have suggested that VEGFC-expressing pro-lymphangiogenic macrophages are responsible for mediating lymphangiogenesis in breast cancer, showing that paclitaxel-induced lymphangiogenesis could be ameliorated by depleting this population of cells." (PMID 29976154, 2018). "The lymphangiogenic VEGFC may facilitate invasion by allowing tumor cells to travel through the lymphatics, a commonly used route of metastasis in breast cancer." (PMID 23667446, 2013).
breast carcinoma (continued). "Some researches have indicated that survivin and vascular endothelial growth factor-C (VEGF-C) may take part in the course of lymphatic metastasis of breast cancer." (PMID 22607367, 2012). "The genes belonged to a variety of biological functions such as cell motility and invasion (Cdc42, ITGB2), cell cycle (EGR1, RRM2) or signal transduction (VEGFC), indicating that expression of E-cadh and P-cadh in breast cancer cells have a significant impact on their overall genetic program." (PMID 19257890, 2009). "Furthermore, ZKSCAN5 is positively correlated with the expression of VEGFC and could be a valuable prognostic marker for poor survival of breast cancer." (PMID 35600335, 2022). "Previous study has shown that ADAMTS1 could physically interact with VEGFC in breast cancer cells." (PMID 30131072, 2018). "However, stress did not elevate Vegfc expression in CD11b+F4/80+ macrophages isolated from primary mammary tumours, suggesting that there may be additional stromal sources of stress-regulated VEGFC." (PMID 26925549, 2016). "In addition to having a pivotal role in basal breast cancer growth and metastasis, the secreted factors implicated in our previous study (IL6, CSF2, CCL5, VEGFA, and VEGFC) may also serve critical roles in other subtypes of breast cancers." (PMID 26173622, 2015). "In breast cancer models, restoring SOD3 under VEGFC knockdown conditions enhances primary tumor development and metastasis, indicating a synergistic relationship between VEGFC and SOD3 in tumor progression." (PMID 41028519, 2025). "To further investigate the transcription mechanisms of ZKSCAN5 on regulating VEGFC expression in breast cancer cells, we confirmed the binding site of ZKSCAN5 on the VEGFC promoter." (PMID 35600335, 2022). "Our results characterise the role of ZKSCAN5 in regulating VEGFC transcription and predict ZKSCAN5 as a breast cancer therapeutic target." (PMID 35600335, 2022). "As a new clinical prognostic marker for breast cancer, ZKSCAN5 has a positive correlation with VEGFC expression." (PMID 35600335, 2022). "The aim of this study was to determine the association of dietary folate and cobalamin with plasma levels of Angiopoietins (ANG), vascular endothelial growth factor-C (VEGF-C) and tyrosine kinase receptor-2 (Tie-2) of primary breast cancer patients." (PMID 31619709, 2019). "While NO stimulated the vascular endothelial growth factor-C (VEGF-C) expression and promoted lymph node metastasis in breast cancer." (PMID 29357836, 2018). "Based on the results of previous studies, we chose the miR-122 target genes ADAM10, Bcl-w, VEGFC, PKM2, NOD2, IGF1R and NDRG3 to explore the downstream genes in breast cancer." (PMID 29200969, 2017). "VEGFC is significantly overexpressed in HER2+ breast cancer relative to basal breast cancer in TCGA (p-value of 0.005) and in HER2 + breast cancer relative to all other subtypes in METABRIC data (p-value of 4 × 10−6)." (PMID 26173622, 2015). "Though VEGFC mRNA expression in HER2+ breast cancer is less well-understood, recent study showed that HER2/neu expression correlates with VEGFC and lymphangiogenesis in lymph node-positive breast cancer." (PMID 26173622, 2015). "Our previous study found that both ECM1 and vascular endothelial growth factor-C (VEGF-C) have a synergistic effect on lymphangiogenesis, so as to facilitate lymphatic metastasis of breast cancer." (PMID 24779890, 2014). "In present study, we aimed to investigate the relationship between vascular endothelial growth factor-C (VEGF-C) and COX-2 in human breast cancer, and correlations with lymphangiogenesis and prognosis." (PMID 18190720, 2008). "Vascular endothelial growth factor C (VEGF-C) is a lymphangiogenic factor over-expressed in highly metastatic, cyclooxygenase (COX)-2 expressing breast cancer cells." (PMID 17912247, 2007).
breast carcinoma (continued). "VEGFC and COX2 are significantly correlated with lymphangiogenesis and a poor prognosis of invasive breast cancer, including increased lymph node metastasis and worse overall survival of breast cancer patients." (PMID 38218743, 2024). "VEGFC binds to VEGFR2 and plays a role in lung, colorectal, and breast cancer cells." (PMID 35794983, 2022). "A study demonstrated that primary breast tumours induce sentinel lymph node lymphangiogenesis and that tumour-derived VEGFC plays an important role in their lymphangiogenesis in breast cancer, but not VEGFD." (PMID 35600335, 2022). "Moreover, we show that expression of both miR526b and miR655 is positively correlated with expression of angiogenesis (CD31 and VEGFA) and lymphangiogenesis markers (VEGFC, VEGFD, and LYVE1) in human breast cancer tissue." (PMID 31277414, 2019). "We found that CCR7 mRNA expression in human breast cancer tissues positively correlates with the expression of lymphatic endothelial markers LYVE-1, podoplanin, Prox-1, and vascular endothelial growth factor-C (VEGF-C)." (PMID 25744065, 2015). "In breast cancer cells, secreted LOXL2 enhances lymphatic endothelial cell invasion through AKT and ERK signalling and stimulates fibroblasts to secrete pro-lymphangiogenic factors such as vascular endothelial growth factor C (VEGF-C) and stromal cell-derived factor 1 (SDF-1α)." (PMID 37762708, 2023). "designed a randomized controlled trail in 80 breast cancer patients, they reported that the total intravenous anesthesia can inhibit the release of vascular endothelial growth factor C (VEGF-C) in breast surgery, yet with no significant benefice in the short-term recurrence rate of breast cancer." (PMID 32928121, 2020). "Interestingly, we found that expression of VEGFC and SOD3 positively correlate not only in breast cancer (using two different human data sets) (Bittner Multi-cancer data set, unpublished data, 1 January 2006) but also in kidney and cervical cancers (Bittner Multi-cancer data set)." (PMID 25358638, 2014). "Triple negative breast cancer cells overexpress VEGF and VEGFC but do not express VEGFR." (PMID 34067671, 2021). "Furthermore, the expression level of VEGFa mRNA, but not VEGFc mRNA, is increased more than 3 folds in NCOA1-overexpressing mammary tumors in Tg(MMTV-NCOA1) × Tg(MMTV-TVA/RCAS-PyMT) mice when compared with that in Ncoa1 WT mammary tumors in Tg(MMTV-TVA/RCAS-PyMT) mice." (PMID 26287601, 2015).